IL1A (interleukin 1 alpha)
Diseases named in the same sentence as IL1A in open-access papers (continued):
Sharing a sentence is not in itself a finding about the gene and the disease.
cancer (continued). "However, activation of the cell death program leads to the release of inflammatory mediators IL1A and IL18RAP, which continue to promote cancer development." (PMID 35923703, 2022). "Conversely to HCV-infected patients with resolved HBV infection, non-HCV-infected patients with HBV reactivation during anti-cancer/immunosuppressive therapy or BMT had significantly higher IL-1α and -1β levels than did those without HBV reactivation." (PMID 36207368, 2022). "Additionally, the uterine microbiome can stimulate the production of pro-inflammatory cytokines in endometrial cells, including IL-1α, IL-1β, IL-17α, and TNF-α, which are involved in the carcinogenesis of various cancers." (PMID 35628566, 2022). "As revealed by IHC staining analysis, the proteins of CYBB, IL1A, IL1B, and SLC25A5 were mainly found in cancer cells’ nucleus, cytoplasm, and membranes; brown staining indicated positive staining; and these NRG proteins were either weakly expressed or not expressed in normal tissues." (PMID 36253777, 2022). "This is of importance, as the SASP from IL-1α-depleted fibroblasts was shown to be less able to induce invasion of cancer breast cells compared to the SASP from wild type senescent fibroblasts, suggesting an important role of IL-1α for the oncogenic properties of the SASP." (PMID 34943822, 2021). "As IL1A and IL6 are two important pro-inflammatory cytokines in human cancers, we speculated that the hypoxic stress in the lung tumor promotes the secretion of IL1A and IL6." (PMID 34362882, 2021). "The application of anti-IL-1α mAb MABp1 can greatly improve the survival of patients with advanced non-small cell lung cancer, ovarian cancer and other refractory cancers, without obvious side effects." (PMID 34625124, 2021). "Moreover, the expressions of IL-1α, SRY, Oct4, IL-6, and TGF-β in BMSCs were markedly increased by cancer cell-derived EVs." (PMID 34746322, 2021). "As there is evidence suggesting that IL-1α, IL-1β, and IL-1RA are involved in the pathogenesis of HNSCC and can be detected in the saliva of cancer patients, different studies have explored their possible use as diagnostic or prognostic biomarkers for this cancer." (PMID 35048046, 2021). "After metastasis, pro‐inflammatory cytokines, including Il1α, Il1β, Il6, Il18, and TNF‐α, were significantly induced in lung metastases, indicating that inflammatory cytokines may play a positive role in cancer metastasis." (PMID 34766117, 2020). "Furthermore, our study showed the DMU-214-triggered decrease in the expression of IL1A and IL15, which are involved in enhancing cancer cell proliferation." (PMID 32046103, 2020). "This would suggest that the neutralizing IL-1α antibody could be a useful tool to modulate CD137 expression, and thus could be employed to impact immune functions in the context of cancer immunotherapy." (PMID 31288851, 2019). "It is currently unclear how the activation of K-ras could lead to increased expression of IL-1α, or which transcription factor(s) might bind and regulate the CD137 transcription in cancer cells." (PMID 31703738, 2019). "The influence of IL-10 on more severe cancer disease is explained by antagonistic effect of IL-10 on the formation of pro-inflammatory cytokines (IL-6, TNF, IL-1α, IL-1β, IL-12) and inhibition of the inflammatory response, which plays an important role in the development of cancer." (PMID 27547238, 2016). "These complex cross-talk events among EGF, EGFR, IL-1α, ADAM, JAK, Src and other signaling molecules may play an important role in BQ chewing-related diseases (e.g., cancer, OSF, and atherosclerosis)." (PMID 26919242, 2016). "Silencing of SMAD7 reduced the ability of IL-1α to enhance the stimulating effect of PSC conditioned medium on the migration of the carcinoma cells compared to conditioned medium from non-silenced PSCs." (PMID 27473228, 2016).
cancer (continued). "Thus, in highly metastatic cancer cells, the enhanced expression of CXC chemokines in response to endogenous IL-1α seems to stimulate macrophage migration." (PMID 24924428, 2014). "Also note that two genes, IL1A and BCL6, were identified differentially expressed in both the normal and the cancer cells." (PMID 24725556, 2014). "Whereas primary HOSE cell cultures show highly IL-1α responsive COX-2 and 11βHSD-1 gene expression, neither gene in the cancer cell lines responded markedly to IL-1α." (PMID 15870720, 2005). "Moreover, cancer-associated fibrosis is marked by chronic inflammation within cyto/chemokines (i.e., IL-6, IL-8, IL-17A, and IL-1α), and growth factors (i.e., SDF-1, HGF, PDGF, and TGF-β) are released by both malignant and non-cancer cells, contributing to tumor cell proliferation and invasion." (PMID 40649899, 2025). "Neither treatment by human CM nor human CM plus IL-1α agonist affected cancer cell migration." (PMID 36982207, 2023). "Plasma profiles of IL-1α and IL-1β during the perioperative period exhibited high variation between patients and did not convey a discernable trend among specific cancer types." (PMID 38067195, 2023). "In the TME, IL-1α secreted from OSCC cells is not only able to promote the proliferation of CAFs but can also upregulate the secretion of cytokines, including the C-C motif ligand (CCL) 7, the C-X-C motif ligand (CXCL) 1, and IL-8, that promote cancer progression in human OSCC patients." (PMID 35740551, 2022). "Since cancer cells of epithelial origin can express IL-1R2, it is possible that in our case cetuximab/EGFR inhibition may be inducing the release of IL-1β as well as IL-1α but we are unable to detect IL-1β due to rapid binding by sIL-1R2." (PMID 30890189, 2019). "Thus, targeting glucose/NEDD4-dependent H3 ubiquitination and subsequent transcription of IL1α/IL1β and GCLM may be an effective way to target cancers." (PMID 28300060, 2017). "Hence, targeting this newly identified signaling pathway, such as NEDD4, Gcn5 or their transcriptional targets including IL1α, IL1β and GCLM may be promising approaches for cancer therapy." (PMID 28300060, 2017). "Whether or not cancer necroptosis was essential for the release of IL-1α is difficult to judge, because both cell death and IL-1α release were dependent on regulation by RIPK3." (PMID 25888634, 2015). "However, neither IL-1α nor IL-1β was detected in the supernatants of gastric fibroblasts under normal conditions or when incubated with cancer cell–conditioned media." (PMID 23593346, 2013). "The stimulation of COX-2 in HOSE cells (28-fold, P<0.001) and relative lack of stimulation in SKOV-3, BG-1 and PEO-4 cancer cell lines, in response to IL-1α, therefore, suggests that these cancer cell lines have lost the ability to induce a normal inflammatory response." (PMID 15870720, 2005). "Finally, addition of CXB during pre-treatment of COX-2WT 4T1 cells with 5-FU reduced the levels of IL-6 and IL-1α detected in the peritoneum, further exposing the major contribution of COX-2 enzymatic activity for the inflammatory properties of CTX-treated cancer cells in vivo." (PMID 35440553, 2022). "Three pro-inflammatory cytokines (IL-1β, IL-1α, TARC for adolescents with cancer and IL-1β, I-309, oncostatin-M for adolescents without cancer) demonstrated significantly higher levels in FF of adolescents compared to oocyte donors." (PMID 39211054, 2024). "These correlations were independent of human HCC stage, suggesting that the downregulation of SPTBN1 and the upregulation of IL-1α, IL-1β and IL-6 occur in HCC throughout all stages of cancer progression, and also irrespective of human hepatitis virus status." (PMID 33754058, 2021). "Our datasets suggest that in response to MIT‐mediated chemotherapy, cancer cells also become senescent, but they do not express a typical SASP, as the expression levels of a number of key SASP factors such as IL1α, IL6, CXCL8, and MMP1 remained largely unchanged." (PMID 40265973, 2025).
cancer (continued). "Moreover, S100A13 overexpression promotes oncogene Ras-induced cell senescence (Ras OIS), Doxorubicin-induced cancer cell senescence (TIS) and replicative senescence, while impairment of non-classical secretory pathway of IL-1α delays cellular senescence." (PMID 30670674, 2019). "This suggests that these cancer cells might have more than one pathway to promote CD137 expression and thus are not exclusively dependent on IL-1α for stimulation." (PMID 31703738, 2019). "However, we observed that the neutralization of IL-1α by antibody failed to decrease CD137 expression in 3 out of the 4 cell lines tested, suggesting that most cancer cells might have multiple pathways to activate the CD137 expression and thus are not highly dependent on IL-1α for stimulation." (PMID 31288851, 2019).
bacterial infection (37 papers, 2012 to 2025). "To evaluate the association between bacterial infection, IL‐1α, neutrophilia, and BOS, we developed an in vitro model of P. aeruginosa infection of the airway epithelium and its subsequent effects on fibroblast activation." (PMID 26714197, 2016). "In addition, IL-1α is primarily associated with inflammatory during the pathogenesis induced by bacterial infection." (PMID 32733891, 2020). "Analysis of proinflammatory cytokines and chemokines at different time points showed significant upregulation of Tnf, Mmp14, Il1b, Il1a, Il17ra, Cxcl1, Cxcl2, Ccrl2, Ccl3, Ccl4, and Ccl9 after bacterial infection." (PMID 41117166, 2025). "Common interleukins released by keratinocytes during bacterial infections include IL-1α, IL-6, IL-36, and TNF-α." (PMID 40856949, 2025). "The inflammatory factors associated with bacterial infection of IFN-γ, TNF-α, IL-1α, and IL-6 were measured by ELISA analysis." (PMID 36937280, 2023). "In our previous study, we demonstrated that IL-1α, IL-1β and IL-1Ra were increased in cirrhotic patients and increased IL-1Ra levels predicted bacterial infection events." (PMID 34648567, 2021). "The exposure of cells to bacterial infection stimulates the intracellular expression of IL-1α as well as resulting in membrane IL-1α expression." (PMID 34943999, 2021). "PM2.5-treatment plus bacterial infection inhibited the production of proinflammatory cytokines including IL-1α, IL-1β, and TNF-α, thereby enhancing bacterial infectivity." (PMID 32753046, 2020). "Furthermore, TNFα and IL-1α play crucial roles in inducing chemokines and recruiting MΦs and T cells necessary for eliminating intracellular bacterial infections and maintaining the protective microenvironment of tuberculous granulomas." (PMID 41189022, 2025). "The cytokines TNF-α, IL-1α and IL-6 promote the synthesis of acute phase proteins such as C-reactive protein, by hepatocytes, the concentration of which is significantly increased during bacterial infection or tissue damage." (PMID 36937280, 2023). "So, IL-1α might best be considered as a factor that further stimulates innate immunity when there is host cell damage in addition to bacterial infection." (PMID 25395028, 2014). "As IL-1α is increased in the CF airway during bacterial infection, we hypothesize defective apoptotic signaling and efferocytosis may play a role in IL-1R-activated neutrophilic inflammation in the CF airway before and after bacterial colonization of the CF airway." (PMID 32328066, 2020). "Many of the highly expressed genes encode important factors of the innate immunity such as IL-1A, IL-6, IL-23A, TNF superfamily proteins, CCL and CXCL chemokine families and NFκB and STAT4 regulators and belong to common expression pattern mounted by host cells upon bacterial infection." (PMID 32070192, 2020). "Injection of IL-1α, TNFα, OSM, IL-22 and IL-17 together in the wound edges induced delayed wound healing similar to that induced by the bacterial infection." (PMID 36275755, 2022). "Although the biogenesis of IL-1α and its distinctive role in the inflammatory process remain poorly defined, recombinant murine TNF-α and IL-1α can protect mice from lethal bacterial infections." (PMID 34943999, 2021). "Our study highlights the importance of caspase-11 in a non-bacterial infection, integrating the IFN-β/caspase-11 axis with IL-1α release and resistance to P. brasiliensis challenge." (PMID 31425553, 2019). "The production of IL-1β, IL-1α, TNF-α, and IL-6 was completely dependent on bacterial infection, but low levels of MCP-1 and MIP-1α were already detected in the supernatants from uninfected cultures." (PMID 30455194, 2019). "Whereas LPS, widely used to mimic bacterial infections in vitro, evoked distinct pro-inflammatory responses in HBMEC, expressed by mRNA and protein increases for CXCL5, IL-1α, IL-1β, IL-6, IL-8, MCP-1, MCP-3, and TNF-α, Ureaplasma spp." (PMID 31336668, 2019).
bacterial infection (continued). "Both IL-1α and IL-1β were detectable in bronchioalveolar lavage fluids (BALs) of young children with CF in the absence of bacterial infection, highlighting potential for inflammation of the CF airway under sterile inflammation." (PMID 32765492, 2020). "Expression of IL-1α and IL-33/ST2 has been reported in several bacterial infectious diseases." (PMID 27667993, 2016). "IL-1α is a key mediator of the sterile inflammatory response, but is not generally critical for the response to bacterial infection." (PMID 26500655, 2015). "The inability to detect other cytokines, like IL-1α or IL-6, that are known to be produced by keratinocytes in response to bacterial infection may be attributable to several, not further investigated factors." (PMID 40387366, 2025). "Primary cells treated with both Pam3CSK4 and GM-CSF showed increased intracellular levels of IL-1α and IL-1β protein, but did not release IL-1α and IL-1β, suggesting that primary human monocytes require an additional signal provided during bacterial infection to release IL-1 cytokines." (PMID 40470942, 2025). "These independent studies suggest that pyroptosis might lead to extrusion of infected enterocytes and promote bacterial infection in vivo even in the absence of IL-1α, IL-1β, and IL-18." (PMID 30138458, 2018). "Hence, bacterial infection or inflammatory markers did not seem to directly influence the recruitment of CD161+CD4+ T cells in the cervical compartment, but elevation of IFN-γ and IL-1α contributes to maintaining high level of CD161 cell surface expression in the FRT." (PMID 28894259, 2017).
inflammation (32 papers, 2011 to 2026). Aberrant reaction of the microcirculation characterized by movement of fluid and leukocytes from the blood into extravascular tissues. "For example, it is known that IL1α co-localizes with nuclear material, and extracellular nuclear contents, including DNA, have been found in association with eosinophilic inflammation." (PMID 33801398, 2021). "In addition, other pro-inflammatory cytokines such as IL-1α, IL-12 and IL-18 are linked to pancreatic islet inflammation." (PMID 32126084, 2020). "To clarify the contribution of necroptosis to IL-1α production in a mouse model of respiratory inflammation, we analyzed immune responses in the lungs of WT, Ripk1DN/DN, or Ripk3−/− mice following airway administration of emricasan." (PMID 41429777, 2025). "IL-1α and IL-1β, acting through the IL-1 receptor (IL-1R), further propagate pericardial inflammation, with IL-1α serving as an early alarmin and IL-1β enhancing the immune response." (PMID 41136179, 2025). "The release of IL-1α from damaged intestinal epithelial cells can contribute to chronic intestinal inflammation." (PMID 36647141, 2023). "Both TRPV1 and TRPA1, members of the TRP channel superfamily, play a key part in lung inflammation via the release of neuropeptides (substance P) and proinflammatory factors, such as leukotriene, IL-1α, and TNF-α, which cause primary airway inflammation." (PMID 37836429, 2023). "According to published data, a deficit of IL-1α and/or IL-1β is followed by uncontrolled bacilli growth and pulmonary inflammation in mice." (PMID 34442871, 2021). "Taken together, the pathogenesis of chronic intestinal inflammation is characterized by a robust elevation of IL-1 family members promoting agonist activity, including IL-1α and IL-1β, whose primary source are LPMCs of myeloid lineage." (PMID 23847622, 2013). "In vivo, treatment of Aspergillus-infected Il1r1–/– mice with anakinra increased the ratio of LC3-II/I and decreased p62, a ubiquitin-binding protein that is selectively degraded by autophagy; inhibited IL-6, IL-17A, IL-1β, and IL-1α production; increased IL-10; and ameliorated lung inflammation." (PMID 34847078, 2022). "However, IL-1α has also been reported to be an alarmin and a master cytokine that induces acute lung inflammation via pro-IL-1β synthesis and IL-1β release." (PMID 32316988, 2020). "Therefore it seemed that expression of either IL-1α or IL-1β helped controlling acute lung inflammation induced by M. tuberculosis infection." (PMID 25400917, 2013). "In contrast to these findings, both IL-1α−/− and IL-1β−/− mice exhibit defective Th2-mediated resistance to the helminth T. muris, and IL-1α, IL-1β have been reported to be necessary for promoting airway inflammation and particle-induced pulmonary inflammation, respectively." (PMID 23935505, 2013). "Pro-inflammatory cytokines such as IL-1α, IL-1β, IL-2, IL-5, IL-6, IFN-γ, MCP-1, MIP-1α, MIP-1β and TNF-α are shown to play an essential role in inducing age-related chronic inflammation." (PMID 31181695, 2019). "The qPCR results indicated that both PACEL and three indole analogues could alleviate DSS-induced intestinal inflammation in mice by inhibiting pro-inflammatory cytokines (MMP7, IL1α) and down-regulating BMP8B expression, thus preventing carcinogenesis of normal colonic epithelial cells." (PMID 37927593, 2023). "In a model of hypercholesterinemia, lack of IL-1α and IL-1β was able to prevent liver inflammation." (PMID 33202693, 2020). "We also reported here that IL-1α is not involved in cartilage damage and synovial inflammation as, in the MNX model, the phenotype of IL-1α−/− was similar to that of WT mice." (PMID 28659793, 2017).